ACAN (aggrecan)
Diseases named in the same sentence as ACAN in open-access papers (continued):
Sharing a sentence is not in itself a finding about the gene and the disease.
rheumatoid arthritis (21 papers, 2006 to 2025). A chronic, systemic autoimmune disorder characterized by inflammation in the synovial membranes and articular surfaces. "Rheumatoid arthritis (RA) can be initiated and driven by immune responses to multiple antigenic epitopes including those in cartilage proteoglycan (PG, aggrecan) and type II collagen." (PMID 34063326, 2021). "Cathepsin B overexpression results in the onset of osteoporosis, rheumatoid arthritis, and certain forms of cancers due to the excessive degradation of the proteins aggrecan, tenascin C, fibronectin, and collagen type 1." (PMID 34827106, 2021). "This study was performed to evaluate the effects of 15-month anti-tumor necrosis factor α (anti-TNF-α) therapy on the aggrecan turnover of female rheumatoid arthritis (RA) patients." (PMID 32392807, 2020). "Previously, GrB-mediated cleavage of another extracellular PG, aggrecan, was described and other unidentified cartilage PGs, were shown to be cleaved in rheumatoid arthritis." (PMID 22479366, 2012). "Our data are consistent with previous results showing that cartilage aggrecan degradation proceeds in a two-state manner in rheumatoid arthritis." (PMID 19371408, 2009). "The biological association between ACAN and IL-18BP is not clear, but IL-18BP have shown to suppress IL-17-induced osteoclastogenesis and rectifies T cell imbalance in rheumatoid arthritis." (PMID 40625747, 2025). "Additionally, TNF-α is up-regulated in collagen and aggrecan cartilage destruction in joints affected by rheumatoid arthritis and is responsible for necroptosis in injured and inflamed tissue." (PMID 37443993, 2023). "Recently, the presence of CD4+ T cells reactive to citrullinated aggrecan epitopes in patients with rheumatoid arthritis (RA) has been described." (PMID 33277543, 2020). "Cellular immunity to proteoglycan has also been described in patients with juvenile rheumatoid arthritis, and immunoreactive fragments of PG aggrecan and anti-PG antibodies have been demonstrated in the synovial fluids of patients with RA." (PMID 24605340, 2014). "Aggrecan autoantibodies have been described in SLE, rheumatoid arthritis, systemic sclerosis, Sjögren’s syndrome, and ankylosing spondylitis." (PMID 26081107, 2015). "Aggrecanases are known to be responsible for aggrecan degradation in articular cartilage in diseases such as OA and rheumatoid arthritis (RA), and cleave the aggrecan core protein at several specific sites; one is between Glu373 and Ala374 which generates the G1-NITEGE fragment." (PMID 19778432, 2009). "For instance, rheumatoid arthritis (RA) patients exhibit memory CD4+ T cells specific for various citrullinated antigens, including citrullinated aggrecan and citrullinated vimentin, which correspond to autoantibodies directed against citrullinated antigens and proteins in these patients." (PMID 32106536, 2020). "Similar findings have been observed in rheumatoid arthritis, where subjects with destructive disease (that required joint replacement) had higher initial levels of 1-F21 aggrecan compared to subjects with non-destructive disease when evaluated up to 12 years later." (PMID 33261598, 2020). "This may explain why, while MMP-3 levels in SF of rheumatoid arthritis (RA) patients are extremely high, depletion of MMP-3 in animal models does not prevent cleavage of aggrecan, nor does it prevent or reduce cartilage destruction observed in specific forms of arthritis." (PMID 16859524, 2006).
osteochondritis dissecans (15 papers, 2011 to 2025). A rare bone disease characterized by an acquired idiopathic necrotic lesion of subchondral bone with the formation of a sequestrum, which may detach to form loose bodies in joints. "ACAN gene mutations were found to cause Aggrecan-related bone disorders (spondyloepimetaphyseal dysplasias,spondyloepiphyseal dysplasias, familial osteochondritis dissecans and short stature syndromes)." (PMID 38494255, 2024). "Taken together, this supports a link between missense ACAN variants affecting the aggrecan G3 domain and hereditary osteochondritis dissecans." (PMID 35338222, 2022). "Mapping these and other ACAN variants linked to hereditary skeletal disorders showed a clustering of osteochondritis dissecans-linked variants to the G3 domain." (PMID 35338222, 2022). "Another missense ACAN variant was linked to familial osteochondritis dissecans (fOCD) with short stature and early onset osteoarthritis." (PMID 35338222, 2022). "The mutations in the ACAN gene can be classified into four categories: spondyloepiphyseal dysplasia, Kimberley type (SEDK, OMIM#608361); spondylo-epi-metaphyseal dysplasia, aggrecan type (SEMD, OMIM#612813); osteochondritis dissecans (OCD, OMIM#165800); and short stature and advanced bone age." (PMID 36118854, 2022). "Osteochondritis dissecans (OCD) is a disabling condition characterised by abnormal deposition of aggrecan in cartilage and the appearance of cracks in the cartilage and subchondral bone." (PMID 32867198, 2020). "Mutations in ACAN result in a broad phenotypic spectrum of non-lethal skeletal dysplasias including spondyloepimetaphyseal dysplasia, spondyloepiphyseal dysplasia, familial osteochondritis dissecans and various undefined short stature syndromes associated with accelerated bone maturation." (PMID 27353333, 2016). "Mutations in the human aggrecan gene (ACAN or AGC1) lead to a broad range of non-lethal skeletal dysplasia including spondyloepimetaphyseal dysplasia (SEMD), osteochondritis dissecans with early onset of OA, and various short stature syndromes with accelerated bone maturation." (PMID 30813547, 2019).
intervertebral disc degeneration (12 papers, 2012 to 2024). "Patients with short alleles of aggrecan with repeat numbers ranging from 18 to 21 (the most common being 26–28 repeats) had the lowest amount of chondroitin sulfate chains in aggrecan molecules, which was associated with a high risk of developing intervertebral disc degeneration (IVDD)." (PMID 37893088, 2023). "One of the most notable alterations in intervertebral disc degeneration is the reduction in Aggrecan (proteoglycan) content." (PMID 38352058, 2024). "Because of these vital functions, reduced aggrecan within the IVD is a principal factor in the intervertebral disc degeneration." (PMID 36431001, 2022). "MMPs are essential in the catabolism of ECM in intervertebral disc degeneration, as well as Adamts‐5, which are mainly responsible for the degradation of aggrecan." (PMID 29575654, 2018). "Additionally, during the process of intervertebral disc degeneration, there is an increase in the content of fibrous connective proteins, further depleting the levels of Aggrecan." (PMID 38352058, 2024). "The aim of this investigation, therefore, was to study the association of the aggrecan gene (ACAN) variable number tandem repeat (VNTR) and the vitamin D receptor (VDR) rs731236 (TaqI) polymorphisms, with lumbar intervertebral disc degeneration in a population in the North of Iran." (PMID 35919638, 2022). "Elevated levels of proinflammatory mediators increased Aggrecan and Collagen II degradation, and increased degradation of extracellular matrix (ECM) has been widely regarded as a significant contributor to intervertebral disc degeneration (IDD)." (PMID 32228440, 2020).
spondyloepimetaphyseal dysplasia (12 papers, 2016 to 2024). An osteochondrodysplasia that results in abnormalities of bone growth in the vertebral column, epiphysis, and metaphysis. "Homozygous ACAN variants lead to spondyloepimetaphyseal dysplasia, aggrecan type (SEMD, OMIM#612813)." (PMID 35620465, 2022). "Homozygous ACAN mutations lead to spondyloepimetaphyseal dysplasia, aggrecan type (SEMD, OMIM#612813)." (PMID 31841439, 2020). "Among the other aggrecanopathies, spondyloepimetaphyseal dysplasia, aggrecan type, is an autosomal recessive condition also caused by an aggrecan mutation with a phenotype of extreme short stature, macrocephaly, and radiographic changes." (PMID 31206541, 2019). "Furthermore, homozygous or heterozygous mutations in ACAN cause spondyloepimetaphyseal dysplasia Aggrecan type or dominant familial osteochondritis dissecans, respectively." (PMID 34539746, 2021). "Interestingly, both biglycan and aggrecan, two proteoglycans altered in MSS, have been associated with spondyloepimetaphyseal dysplasia, spondyloepiphyseal dysplasia, and chondrodysplastic dwarfism." (PMID 39180052, 2024).
spondyloepiphyseal dysplasia (10 papers, 2016 to 2024). An osteochondrodysplasia that results in abnormalities of bone growth in the vertebral column and the epiphysis. "For humans, a single base pair insertion in ACAN resulted in spondyloepiphyseal dysplasia type Kimberly, characterized by shortened limbs and trunk." (PMID 31351448, 2019).
joint disease (9 papers, 2008 to 2025). "Patients with aggrecan (ACAN) deficiency present with dominantly inherited short stature, as well as early-onset joint disease." (PMID 39502477, 2024). "Inhibiting aggrecanase activity may offer advantages over collagenase inhibition, as the loss of aggrecan in cartilage is one of the earliest events in the onset of joint diseases such as OA." (PMID 41020853, 2025). "In the two groups most strongly associated with high joint disease activity, acute inflammatory arthritis and acute knee injury, a majority of the aggrecan fragments were indeed shown to be the result of aggrecanase IGD activity, whereas the other groups had much lower proportions." (PMID 19545413, 2009). "In joint diseases, aggrecan is proteolyzed mainly by matrix metalloproteases (MMPs) and aggrecanases and the released aggrecan fragments from cartilage can be measured in synovial fluid, blood serum, and urine." (PMID 34805399, 2021). "Gene expression analysis showed a reduction in the expression of some inflammatory joint disease markers, such as Aggrecan and types I and II Collagen, after extract and IL-1β treatment." (PMID 33072083, 2020). "Aggrecanase activity is normally very low in adults, but detection of aggrecan fragments/neoepitopes is increased in the serum of horses with joint disease." (PMID 28348888, 2017). "Although proteases, such as matrix metalloproteases (MMPs), cathepsins and calpains, are involved, aggrecanase plays a major role in aggrecan degradation in murine and human joint disease." (PMID 19545413, 2009). "The proportion of ARGS of all aggrecan as a marker for joint disease had a sensitivity of 65% and a specificity of 96%." (PMID 19545413, 2009). "The work presented here confirms that aggrecanase cleavage in the IGD is a major contributor to aggrecan degradation in human joint pathology, and extends our understanding of the relative contribution of aggrecanase activity in different human joint diseases." (PMID 19545413, 2009). "ARGS neoepitope aggrecan fragments released into the SF, as detected by western blot or amino acid sequencing, have been associated with joint diseases and have also been detected as a result of normal turnover." (PMID 19545413, 2009). "We hypothesized that ARGS neoepitope concentrations in SF would differ between these groups and be a more sensitive measure of joint disease than previously used aggrecan or sGAG assays." (PMID 19545413, 2009). "We investigated, whether measurement of aggrecan and fragments thereof in serum, could be used as biomarkers for joint-disease in RA patients and furthermore characterized the fragments found in the circulation." (PMID 18507823, 2008). "Although NO has been described as a meniscal product in several joint diseases and as an important mediator of meniscal tissue degradation in several studies, we did not see a stimulating influence of NO on the TNFα-induced GAG release or aggrecan cleavage." (PMID 19778432, 2009).
tendinopathy (9 papers, 2011 to 2022). "The level of aggrecan expression remained stable and was similar in the control and hMSC-treated tendons; other authors found that increased aggrecan mRNA expression is associated with painful tendinopathy." (PMID 24712305, 2014). "Interestingly, however, an overexpression of aggrecan is occasionally associated with tendinopathy." (PMID 35887273, 2022). "In contrast to previous equine and sheep models of tendinopathy, typical chondroid gene expression changes (including increased expression for ACAN and COL2A1) were not apparent in the present study." (PMID 29023489, 2017). "However, MMP1, MMP13, MMP10, ADAMTS5, TIMP3, versican, aggrecan, biglycan, decorin, fibronectin, fibrillin and COMP showed an opposite response with strain compared to tendinopathy." (PMID 23830915, 2013). "Tendinopathy tissue showed decreased expression of a number of cartilage markers including COMP, but expression of other cartilage markers such as aggrecan was not altered." (PMID 21539748, 2011). "However, in contrast to previous equine and ovine models of tendinopathy, increases in GAG content (proteoglycan scores) or increased gene expression of ACAN and COL2A1 were not apparent in the DDFT." (PMID 31013317, 2019).
chondrodysplasia (8 papers, 2016 to 2025). "This syndrome is a congenital form of bovine chondrodysplasia that has been associated with harmful variants in the aggrecan (ACAN) and collagen type II alpha 1 chain (COL2A1) genes." (PMID 40394457, 2025). "Growth plate phenotypes are evident in different hereditary disorders due to ACAN gene variants, with a phenotypic spectrum ranging from mild idiopathic short stature to severe chondrodysplasia." (PMID 35338222, 2022). "This was also observed in Miniature Zebu, in which an aggrecan (ACAN)-associated mutation caused a recessive lethal chondrodysplasia due to a truncated and modified protein." (PMID 32605545, 2020). "Mutations in the human aggrecan gene lead to aggrecanopathies, an increasing group of skeletal dysplasias ranging from mild idiopathic short stature to severe chondrodysplasias." (PMID 30813547, 2019). "In the present study, we found a novel mutation in ACAN resulting in a recessive lethal chondrodysplasia in Miniature Zebu cattle." (PMID 30305023, 2018). "We found a novel mutation in ACAN causing a recessive lethal chondrodysplasia in Miniature Zebu cattle." (PMID 30305023, 2018). "In 2007, two independent mutations affecting the coding region of the aggrecan (ACAN) gene causing lethal chondrodysplasia in Dexter cattle (OMIA 001271-9913) were described." (PMID 27296271, 2016). "These ACAN mutations showed incomplete dominant inheritance, leading to a mild form of dwarfism in heterozygotes, while homozygous animals displayed extreme chondrodysplasia and usually died during gestation." (PMID 27296271, 2016). "Mutations in the ACAN gene also cause chondrodysplasia-like dwarfism in other species." (PMID 32943661, 2020). "This is the first study describing a novel variant in ACAN for chondrodysplasia in Miniature Zebus." (PMID 30305023, 2018). "Taken together, these studies suggest that aggrecan has a significant role in the signaling pathways involved in chondrogenesis, and the lack of which leads to chondrodysplasia." (PMID 31206541, 2019).
dwarfism (8 papers, 2016 to 2022). "Other mouse-models furthermore showed an explicit association between dwarfism and decreased aggrecan expression." (PMID 35563435, 2022). "Chondrodysplastic dwarfism in Miniature horses is an autosomal recessive disorder previously associated with four mutations (D1, D2, D3*, and D4) in the aggrecan (ACAN) gene." (PMID 32943661, 2020). "Although other genes have already been associated with dwarfism in horses, we decided to investigate novel variants in the candidate ACAN gene, since mutations in this gene are related to the birth of dwarf Miniature horses and a dwarf Miniature Shetland pony." (PMID 32943661, 2020). "It has however been suggested that mutations in Aggrecan (ACAN) are associated with chondrodysplasia-like dwarfism in miniature horses." (PMID 27207956, 2016). "In turn, Dexter cattle foetuses affected by dwarfism related to alterations in the ACAN gene die around the seventh month of gestation." (PMID 32943661, 2020). "In addition, tracheal collapse was radiographically observed in the one-year-old Miniature horse with dwarfism (animal 15; homozygous for ACAN:c.6465A > T)." (PMID 32943661, 2020).
schizophrenia (8 papers, 2014 to 2025). A major psychotic disorder characterized by abnormalities in the perception or expression of reality. "Human postmortem studies revealed marked abnormalities of aggrecan and PV-expressing neurons in schizophrenia and bipolar disorder." (PMID 32116542, 2020). "As for instance, in schizophrenia abnormalities CSPG markers such as WFA, aggrecan and chondroitin-6-sulfates in the ECM and associated glia were demonstrated in the amygdala and entorhinal cortex of cases with schizophrenia." (PMID 28860977, 2017). "Recently, it was shown that some CSPGs members like aggrecan, versican, and neurocan were strongly involved in brain disorders like bipolar disorder (BD), schizophrenia, and ADHD." (PMID 24955366, 2014). "In addition, there was a decrease in the immunoreactivity of PNNs positive for WFA and aggrecan in the schizophrenia group." (PMID 40072050, 2025). "The use of post-mortem tissue from the amygdala of schizophrenia patients showed that the number of aggrecan PNNs was decreased, and CSPG abnormalities could be observed." (PMID 40072050, 2025). "For example, decreased expression of reelin is a common characteristic among neurological and mental disorders such as autism, schizophrenia, depression and bipolar disorder, and knock-out mice lacking aggrecan demonstrated improvement in memory in spontaneous object recognition test." (PMID 31632233, 2019).
thoracic aortic aneurysm (8 papers, 2018 to 2022). An aneurysm formed in the wall of the proximal portion of the descending aorta proceeding from the arch of the aorta. "For the case of thoracic aortic aneurysms and dissections (TAADs), Cikach et al6used ribonucleic acid in situ hybridization studies to demonstrate a rise in gene expression of aggrecan and versican in humans and in mouse models." (PMID 35933987, 2022). "These mice died from thoracic aortic aneurysm and dissection (TADD) early with an average survival of 2.5 months and demonstrated increased accumulation of aggrecan when compared to their wild-type littermates." (PMID 35743192, 2022). "A recent study reported that aggrecan has been identified in human normal aorta by the proteoglycanome analysis, but massive aggrecan accumulation and reduced expression of proteoglycanase genes, such as ADAMTS5, was confirmed in thoracic aortic aneurysm and dissection." (PMID 34681829, 2021). "In the aorta, aggrecan degradation is likely to be due to increase in the activity and expression of aortic MMP-2, MMP-9 and Calpain-1 with advancing age33–37, whilst increased ADAMTS levels promote thoracic aortic aneurysm progression." (PMID 29867203, 2018).
knee osteoarthritis (6 papers, 2009 to 2026). "The limited selectivity of most catalytic-site ADAMTS-5 inhibitors and the necessity to preserve aggrecan integrity in early-grade knee osteoarthritis require the development of selective aggrecanase inhibitors." (PMID 41900115, 2026). "The present study was conducted to evaluate the effects of resveratrol as monotherapy on the serum level of type II collagen (Coll 2-1) and aggrecan in patients with knee osteoarthritis." (PMID 34805399, 2021). "Col2 and Aggrecan expression level was a representative marker of cartilage anabolic activity, and MMP13 was an important catabolic marker of knee osteoarthritis progression." (PMID 38742846, 2024). "We determined whether synovial fluid (SF) levels of ARGS-aggrecan distinguish subjects with progressive radiographic knee osteoarthritis (ROA) from those with stable or no ROA." (PMID 21194461, 2010).